IL10 (interleukin 10)
Diseases named in the same sentence as IL10 in open-access papers (continued):
Sharing a sentence is not in itself a finding about the gene and the disease.
Sepsis (continued). "Studies have shown that elevated levels of IL-10, an important immunomodulatory factor that inhibits the release of pro-inflammatory cytokines and impairs effector T-cell function, are strongly associated with poor prognosis in patients with sepsis." (PMID 41001389, 2025). "However, in the context of severe or late-stage sepsis, persistently high levels of IL-10 can contribute to immunosuppression, increasing the risk of secondary infections and poor outcomes." (PMID 41013722, 2025). "Lymphopenia is a marker for sepsis-induced immunosuppression prominently characterized by apoptosis-induced early massive loss of lymphocytes and expansion of immunosuppressive cells (IL-10-producing B cells, regulatory T cells, and myeloid-derived suppressor cells)." (PMID 40817409, 2025). "We highlight that the gene encoding IL-10 is the most sepsis-upregulated IEI gene (170-fold)." (PMID 41229427, 2025). "The IL-10 rs1800896 polymorphism was associated with an increased incidence of complications (OR = 1.6, 95% CI: 1.2–2.1, p < 0.05), particularly respiratory failure and sepsis." (PMID 40692949, 2025). "In addition to causing significant lymphocyte apoptosis, sepsis gradually impairs the functionality of the remaining circulating lymphocytes by inducing the release of anti-inflammatory cytokines, such as interleukin-10 (IL-10), by antigen-presenting cells." (PMID 40005375, 2025). "For the IL-10-1082 gene, newborns with the AA genotype(P = 0.002,OR = 1.702, 95% CI: 1.218–2.377), as well as those with the AA + GA genotype(P = 0.016,OR = 1.731, 95% CI: 1.108–2.705), had a significantly higher risk of sepsis." (PMID 38848433, 2024). "Subgroups that combine IL-10 or IL-6 with NEWS or SIRS scores could further help identify high-risk individuals who may develop sepsis or require intensive care, allowing clinicians to further help guide treatment." (PMID 39212218, 2024). "Additionally, IL-10 can directly suppress endothelial activation and leukocyte recruitment, attenuating vascular permeability changes that underlie organ dysfunction in sepsis." (PMID 38504987, 2024). "Elevated circulating levels of cytokines such as TNF-α, IL-1β, IL-6, IL-8, and IL-10 have been linked to increased morbidity and mortality in patients with sepsis, suggesting that their removal could be beneficial for treatment." (PMID 39766623, 2024). "Indeed, the appropriate expression of IL-10 has been linked with the survival profits of patients with sepsis, and its ablation led to exaggerated pulmonary inflammation and deadly sepsis." (PMID 38637808, 2024). "We analyzed whether the polymorphism was correlated with the cytokine expression of IL1β, IFNα2, IFNγ, TNF-α, IL-33, IL12p70, MCP-1, IL-6, IL-10, IL-17a, IL-18, or IL-23 to further investigate the effect of the polymorphism in sepsis patients." (PMID 38338680, 2024). "As a result of the study, it was possible to establish a significant association of rs1800871 and rs1800896 with sepsis in Asian populations/ It was reported that IL-10 is vital in the inflammatory response of the body to COVID-19 infection and directly correlates with the severity of the disease." (PMID 37390087, 2023). "A meta-analysis conducted in 2022 on the study of the effect of IL10 on sepsis and some inflammatory pathologies confirmed the relationship between the rs1800871, rs1800872, rs1800896 polymorphisms of the IL10 gene and sepsis, and also suggested their role in inflammatory pathologies." (PMID 37390087, 2023). "Further analysis suggests that Interleukin-10 (IL-10), as an anti-inflammatory cytokine associated with both Infective Endocarditis (IE) and sepsis, could potentially serve as a common therapeutic target protein for both diseases." (PMID 38332910, 2023).
Sepsis (continued). "Results of conventional meta-analysis showed that IL-8 manifested the highest pooled sensitivity and specificity in the detection of early-onset sepsis in neonates, which indicates the superior diagnostic properties of IL-8 for neonates as compared to IL-6, IL-8, IL-10." (PMID 38027268, 2023). "In addition, the study found that subjects with IL-10-1082 AA and IL-6-174 CC genotypes had a higher risk of sepsis and increased mRNA levels." (PMID 37753078, 2023). "In our study cohort, high levels of IL-6 and IL-10 at the onset of sepsis (day of study inclusion) were significantly associated with the 30-day mortality as could be expected based on the literature." (PMID 37907989, 2023). "Importantly, MCMV is a pathogen within our infection regimen, and IFN-γ, IL-10, and IL-15 are produced during the sepsis-associated cytokine storm." (PMID 35878936, 2022). "Interestingly, IL-10, an important anti-inflammatory cytokine in sepsis, was negatively associated with the frequency of CECs." (PMID 35251018, 2022). "Furthermore, IL-6 and IL-10 elevation at sepsis onset was associated with an increased risk of NPMODS, proving the efficacy of Th1/Th2 cytokines in predicting sepsis prognosis." (PMID 36544765, 2022). "Furthermore, in a study of adult sepsis patients in the UK, upregulation of both HO-1 and IL-10 were strongly associated with disease severity, and IL-10 concentration was predictive of HO-1 concentration." (PMID 35154104, 2022). "One of the causes of this is high interleukin (IL)-10 production in sepsis." (PMID 35723375, 2022). "Recently, a study on Chinese Han patients also reported that A allele of rs1800896 in IL-10 gene could act as a risk indicator in pneumonia‐induced sepsis signifying A allele as a risk allele for pulmonary infections." (PMID 37521849, 2022). "IL-10 has been proposed as a possible diagnostic marker in the early stages of infection and has been shown to increase the sensitivity and specificity of early sepsis diagnosis." (PMID 35937269, 2022). "In both control and OVR females, sepsis increased the myocardial expression of genes encoding protein associated to inflammation, interleukin-6 (IL-6), IL-10 and IL-18, to cell cycle and survival, Janus Kinase 2 (JAK2) and signal transducer and activator of transcription 3 (STAT3)." (PMID 35322092, 2022). "According to our results, when used in addition to routine blood tests, IL-6 and IL-2 can improve overall diagnostic ability in predicting BI, while IL-10 could increase specificity in early sepsis recognition." (PMID 35582414, 2022). "Additionally, elevated ratios of anti-inflammatory and pro-inflammatory cytokines (e.g., IL-10/TNF) are proposed markers of sepsis-induced immunosuppression and are associated with multiple organ failure." (PMID 35685286, 2022). "Reduced monocyte numbers and M/H ratios at the admission of neonates for suspected sepsis are associated with the development of septic shock, and these parameters were inversely correlated with inflammation markers, such as IL-6, IL-8 and IL-10." (PMID 36368184, 2022). "The right role of IL‐10 is unknown during sepsis, but as it has a dual nature, the diagnostic accuracy can be affected." (PMID 36176597, 2022). "MZ B cells are the most potent IL-10-producing cells in vitro, and increased MZ B cells attenuate early inflammatory responses and primarily exhibited anti-inflammatory effects during the early stage of sepsis in Gpr174-deficient mice." (PMID 36425582, 2022). "The immunoparalysis of DCs increases the levels of IL‐10 and transforming growth factor‐β, and decreases the levels of IL‐6, IL‐12p70 and costimulatory molecules, thus promoting the generation of Tregs and leading to sepsis‐associated immunosuppression." (PMID 36106559, 2022).
Sepsis (continued). "In our collective, patients suffering from postoperative sepsis were characterized by high plasma levels of both pro-inflammatory IL-6 and anti-inflammatory IL-10 at the time of study inclusion, markers associated with disease severity and clinical outcome in sepsis." (PMID 33939725, 2021). "Increasing of IL-10 in severe patients might be related to a compensatory anti-inflammatory response, which may lead to higher proportion of subsequent infections, sepsis, and further raising the death risk." (PMID 33410720, 2021). "Furthermore, the same study conducted on tissue-engineered vascular media demonstrated that the ability of sepsis EVs to restore vascular hypo-reactivity was associated with their ability to increase IL-10 expression in a tissue-engineered blood-vessel model." (PMID 34451925, 2021). "Moreover, in lung tissue derived from Dcn-deficient mice with sepsis, IL-10 levels were decreased and IL-12 and TNFα levels were increased." (PMID 34381449, 2021). "The conclusion was that although prolonged high IL-10 has been associated with developing sepsis altering the immediate IL6-IL10 balance may be beneficial on reducing the acute inflammatory response." (PMID 33013911, 2020). "It has been suggested that monocyte deactivation that occurs during sepsis is caused by IL-10." (PMID 32230846, 2020). "Continuous release of IL-10 might amplify sepsis-induced immunosuppression and thus might augment susceptibility to secondary microbial infections." (PMID 32346013, 2020). "Interestingly, a number of studies have shown that the beneficial effects of MSCs on LPS- or cecal ligation and puncture (CLP)-induced sepsis are linked to an increase in the anti-inflammatory cytokine IL-10." (PMID 32014040, 2020). "showing that increased IL-10 concentrations in sepsis may be due a susceptibility of Th1 T cells to apoptosis, resulting in a prevalence of Th2 T cells, known for their IL-10 production." (PMID 33613540, 2020). "High values of IL-10 (cut-off > 208 ng/L) in association with high values of IL–6 (cut-off > 168 ng/L) are suggestive for disseminated intravascular coagulation (DIC) in neonates with sepsis." (PMID 33419284, 2020). "Elevated levels of IL-10 increase susceptibility to secondary nosocomial infections in sepsis." (PMID 33276561, 2020). "However, the IFN-β treatment reverses the impaired AM function in response to the IL-10 at the late stage of sepsis and decreases the severity of sepsis-associated ALI/ARDS and the associated mortality." (PMID 32849610, 2020). "CMV is reactivated in sepsis and these patients presented a higher risk of developing septic shock and higher mortality rates and our data suggest that IL-10 and NO may be involved in this process." (PMID 31227794, 2019). "Bacterial clearance in vivo may be associated in part to phagocytosis since sepsis-induced mice treated with MSC reduce inflammation (IL-10 and IL-6) while enhancing phagocytosis of S. aureus." (PMID 30975214, 2019). "Of note, PTX3 has been described as associated with IL-10 in atherosclerosis experimental conditions and could help to counteract the pro-inflammatory response observed in sepsis." (PMID 30687307, 2018). "Increased circulating levels of both pro-inflammatory (IL-6) and anti-inflammatory (IL-10) mediators have been associated with poor survival in numerous studies in patients with sepsis, including patients with septic shock randomized to different fluid resuscitation strategies." (PMID 29728790, 2018). "Interestingly, those with septic shock had both higher pro- and anti-inflammatory levels than patients without shock, with the levels of IL-6 and IL-8 positively associated with IL-10 levels, indicating a correlation with sepsis severity." (PMID 30555806, 2018). "Similarly, an increase of IL-10 in peripheral blood was detected in 28% of cases with neonatal sepsis associated with fungal infections, thus reflecting an immunosuppressive state." (PMID 28367457, 2017).
Sepsis (continued). "Finally, we demonstrated that deficiency of IL-10 prevents the increase of Treg cell population in sepsis-surviving mice and improves survival from secondary pneumonia caused by L. pneumophila." (PMID 28374774, 2017). "We investigated the hypothesis based on cytokine imbalance because sepsis-induced immunosuppression is associated with decreased production of inflammatory cytokines and a high IL-10-to-TNF ratio." (PMID 27441846, 2016). "In line with previous studies, carriers of variant allele of TLR4 +896A/G in our febrile acute de-compensated cirrhotic patients did show increased LPS-stimulated IL-10 production and complicated with higher frequency (59%) of severe sepsis compared to wild-type allele carriers (32%)." (PMID 27861595, 2016). "For instance, blocking the anti-inflammatory cytokine IL-10, which is associated with reduced secretion of proinflammatory mediators, at an early stage of sepsis is detrimental to the host, whereas IL-10 suppression later in sepsis is linked with longer survival of the affected animals." (PMID 27774097, 2016). "In the “20 %” group, we confirmed the presence of sepsis associated with hypotension below 65 mmHg, pro-inflammatory balance with high IL-6 levels and augmented IL-6/IL-10 ratio, organ dysfunction, hyperlactatemia, elevated serum creatinine, and hepatocyte centrilobular necrosis." (PMID 27430881, 2016). "Hypersecretion of the anti-inflammatory mediator IL-10 may cause excessive immunosuppression, and reduce the body’s resistance to infection, inducing secondary infection and even leading to sepsis." (PMID 25780458, 2015). "In other words degree of TNF-α in sepsis patients is associated with the production of IL-10." (PMID 26561011, 2015). "In conclusion, our study demonstrates that the alternations in the genotype and allele frequency of IL-1β (−511C/T), TNF-α (−308G/A), TNF-α (−238G/A) and IL-10(−1082G/A) genes are associated with an increased risk of sepsis development in major trauma patients and outcomes." (PMID 26561011, 2015). "Sequence-specific primer based PCR indicated that eight polymorphic loci IL-1α /-889, IL-1β/-511, IL-1R (pstI 1970), TGF-β/ code 10, TNF-α/-308, TNF-α/-238, IL-6/+565 and IL-10/-1082, out of 22 SNPs are significantly associated with sepsis morbidity and outcome." (PMID 26561011, 2015). "In patients with sepsis, a genotype associated with high IL-10 production may lead to greater immunosuppression, resulting in more severe disease burden and outcomes." (PMID 24804995, 2014). "In mice with sepsis, neutralizing IL-10 (interleukin 10) or TGF-β mightrepresent a novel strategy for treating the immunosuppressive condition associated with sepsis." (PMID 24303815, 2014). "Suppressed cytokine production may be mediated by defective mRNA transcription rather than defective secretion, as mRNA expression of two cytokines (IFN-γ and IL-10) were decreased in autophagy-deficient CD4+ cells after sepsis (unpublished data)." (PMID 25029098, 2014). "Furthermore, the authors reported that IL-10-deficient mice showed an earlier onset of lethality after experimental sepsis induced by cecal ligation and puncture as compared with wild type mice." (PMID 25614712, 2014). "Alterations in Treg cells and/or reduction in IL-10 levels can profoundly affect inflammation, susceptibility to skin infections with Staphylococcus, development of allergy, and control of sepsis." (PMID 24489864, 2014). "IL-6 and IL-10 has also been demonstrated to be associated with prognosis of severe sepsis." (PMID 24977412, 2014). "The authors concluded that the allelic variants PLA2G2A, TLR2, TLR5 and IL-10 could influence the risk of sepsis among preterm infants." (PMID 24310803, 2013). "Enhanced concentrations of IL-10 associated with a decrease of the IFN- γ might account for the delay in pathogen eradication during the late stage of sepsis (immunoparalysis)." (PMID 23561467, 2013).
Sepsis (continued). "Interestingly, we found that NAH pretreatment attenuated CLP induction of serum IL-10, an anti-inflammatory cytokine associated with the potentially deleterious counter anti-inflammatory response of sepsis." (PMID 24400155, 2013). "Recently, it was investigated whether polymorphisms in the IL-10 gene promotor affect sepsis susceptibility." (PMID 23853427, 2013). "The late and significant decrease of LPS-stimulated IL-10 may suggest a clinically valuable role of PCT in the control of this cytokine during late stages of sepsis, often associated with immunoparalysis, when IL-10 is reported to play a pivotal role." (PMID 22568957, 2012). "Therefore a protein-microarray for point-of-care testing that simultaneously quantifies the sepsis associated serum proteins IL-6, IL-8, IL-10, TNF alpha, S-100, PCT, E-Selectin, CRP and Neopterin has been developed." (PMID 22438722, 2012). "The inflammatory cytokines associated with sepsis such as Interleukin-6 (IL-6), Interleukin-10 (IL-10) and Interleukin-1β (IL-1β) are found to be correlated with the severity of the disease, the evolution of organ failure as measured by the SOFA score and mortality." (PMID 22035174, 2011). "The high IFN-γ associated with early sepsis may lead to increased IDO activity while high IL10 may sustain or potentially enhance IDO activity throughout the course of the disease." (PMID 21731667, 2011). "In sepsis, that elevated IL-10 serum levels have been associated with poor outcome might be a result of the development of immunoparalysis and increased risk for multiple organ dysfunction syndrome." (PMID 16859504, 2006). "This shift toward an IL-10/IL-6 cytokine profile suggests a reprogramming of macrophage responses toward an immunosuppressive phenotype, a pattern that has been previously associated with poor clinical outcomes in burn patients and is characteristic of the immune-paralysis phase observed in sepsis." (PMID 41010852, 2025). "A recent review described IL-10 as “a pleiotropic cytokine produced by both T cells and macrophages,” capable of suppressing pro-inflammatory cytokine production and antigen presentation, thereby increasing susceptibility to secondary infections in sepsis survivors." (PMID 41300951, 2025). "In addition, treatment with Lactobacillus johnsonii also prevents polymicrobial sepsis-induced liver injury and this was associated with an increase in serum IL-10 suggesting that L. johnsonii may have an overall anti-inflammatory effect." (PMID 38533264, 2024). "In the examination of cytokine levels in the serum and lung homogenate of sepsis mice, quantitative detection results revealed potential challenges associated with utilizing downstream molecules, particularly critical anti-inflammatory cytokines, such as IL-4, IL-10, etc.." (PMID 38255822, 2024). "Also, apoptosis-induced lymphopenia may be caused by neutrophils secreting excessive amounts of IL-10 during sepsis, which hinders T lymphocyte proliferation." (PMID 38474403, 2024). "Therefore, the role of IL-10 and other anti-inflammatory host-derived molecules during P. aeruginosa sepsis is poorly understood and requires further research to confirm its role increasing host susceptibility to severe sepsis and mortality." (PMID 37426029, 2023). "Anti-inflammatory IL-10 cytokine signaling pathway was over-represented, which is a well characterized mediator of immunosuppression in severe sepsis, and IL-4/IL-13 pathways associated with M2 (and reprogrammed) macrophages that have been associated with sepsis." (PMID 37304268, 2023). "In addition, we further explored whether our HLA classifier was associated with the ratio of IL10/TNF in sepsis." (PMID 35685286, 2022). "Moreover, when plasma samples from patients with sepsis and septic shock were analyzed, this phenomenon was exacerbated showing a clear association with the presence of the ~ 67 kDa accessory protein band, and a marked increase in IL-6 and IL-10." (PMID 36536294, 2022).